ID4 (inhibitor of DNA binding 4)
Diseases named in the same sentence as ID4 in open-access papers (continued):
Sharing a sentence is not in itself a finding about the gene and the disease.
lung carcinoma (11 papers, 2010 to 2023). "Previously, our research team performed cDNA microarray screening and identified that Id4 is one of the differentially expressed invasion-associated genes in a panel of lung cancer cells (CL1-0, CL1-1, and CL1-5)." (PMID 31847356, 2019). "Our results showed a higher and more dominant expression of ID1 than those of ID2, ID3, and ID4, particularly in lung cancer cell lines." (PMID 33917757, 2021). "It has been indicated that Id4 can inhibit lung cancer metastasis and mesenchymal-epithelial transition (MET) by binding to slug and promoting E-cadherin expression." (PMID 33936204, 2021). "In the lung cancer, Id4 binds to slug, which interferes with its interaction with E-box promoter, and then suppresses the metastasis of cancer cells." (PMID 33936204, 2021). "To characterize the role of Id4 in lung cancer invasiveness, we first examined the expression levels of Id4 in low invasive CL1-0 and high invasive CL1-5 cells by reverse transcription polymerase chain reaction (RT-PCR) and immunoblotting." (PMID 31847356, 2019). "Although much evidence has suggested the different roles of Id4 in various cancers, the function of Id4 in lung cancer metastasis requires more careful analysis." (PMID 31847356, 2019). "As Id proteins play different roles in various cancers, the identification of how Id4 is involved in lung cancer metastasis has become an urgent need." (PMID 31847356, 2019). "Id4-overexpressing H1299 lung cancer cells were injected into the tail veins of mice, and the formation of metastatic pulmonary nodules was examined for 10 weeks." (PMID 31847356, 2019). "ID4 is involved in cell metabolism and transcription regulation in the pathogenesis of lung cancer and could become a biomarker of lung cancer occurrence and prognosis." (PMID 36661515, 2023). "In addition, Id4 overexpression in lung cancer cells inhibits cisplatin-induced apoptosis via the p38 MAPK pathway." (PMID 33936204, 2021). "Although Id4 plays the opposite role in these cancers, whether the downregulation of Id4 in lung cancer metastasis occurs through epigenetic or non-coding RNA regulation should be further clarified in the near future." (PMID 31847356, 2019). "Here, we found that manipulating the expression of Id4 in lung cancer cells could interfere with cell migratory and invasive abilities, regulate the occurrence of EMT through controlling the Slug/E-cadherin axis in vitro, and affect cancer metastasis in vivo." (PMID 31847356, 2019). "Therefore, we propose that a similar mechanism to that in lung carcinoma cells promotes the degradation of Ascl1 when quiescent hippocampal stem cells express high levels of Id4." (PMID 31552825, 2019). "As expected, both the mRNA and protein expression levels of Id4 were negatively correlated with cell invasiveness in different lung cancer cells (R2 = 0.8336 for Id4 protein expression versus cell invasiveness, and 0.803 for Id4 mRNA expression versus cell invasiveness)." (PMID 31847356, 2019). "Our data not only demonstrate that Id4 may suppress the malignant behavior of lung cancer through EMT regulation but also provide evidence to translate it for the clinical application of lung adenocarcinoma treatment in the near future." (PMID 31847356, 2019). "Moreover, a similar experiment was executed by CL1-5/Id4-overexpressing lung cancer cells and re-confirmed the inhibitory role of Id4 in lung cancer metastasis in vivo." (PMID 31847356, 2019). "This suggests that Id4 may interfere with the malignant behavior of lung cancer cells through EMT regulation." (PMID 31847356, 2019). "Whether E47 or any other bHLH transcription factors participate in inhibiting lung cancer metastasis through Id4 should be further explored." (PMID 31847356, 2019). "However, ID2 and ID4 mRNA expression levels were associated with improved OS in patients with lung cancer without a smoking history." (PMID 32003423, 2020).
lung carcinoma (continued). "Moreover, a low mRNA expression level of ID4 was found to be associated with unfavorable OS in the following categories: Adenocarcinoma, patients with stage 1 lung cancer, sex and patients without a smoking history." (PMID 32003423, 2020). "The expression of Id4 could inhibit the binding of Slug in the E-box promoter region, significantly increase the expression of E-cad, and suppress cancer metastasis in human lung cancer." (PMID 31847356, 2019). "However, the functional role of Id4 and its mechanism of action in lung cancer metastasis remain unclear." (PMID 31847356, 2019). "Moreover, we also found that the expression of Id4 could significantly down-regulate the transcriptional expression of Slug in lung cancer cells." (PMID 31847356, 2019). "All these demonstrate that Id4 may act as an invasion suppressor in lung cancer progression." (PMID 31847356, 2019). "Genes frequently methylated in lung cancer cell lines including SCGB3A1, ID4, CCND2 were found among the most commonly methylated in the lung tumors analyzed." (PMID 20849603, 2010). "MS-MLPA allowed identification of a number of new and possibly interesting epigenetic alterations such as HLTF, ID4, BNIP3, H2AFX, CACNA1G, CACNA1A and TGIF genes, serving to gain more insight into the development of lung carcinomas." (PMID 20849603, 2010). "As expected, the mRNA and protein expression levels of Slug could be regulated by Id4 expressions in CL1-0, CL1-5, and H1299 lung cancer cells." (PMID 31847356, 2019). "Then, the negative correlation between Id4 expression and cell invasiveness was re-evaluated by four additional lung cancer cell lines, including H3255, H1975, H1299, and A549 cells, and a normal bronchus epithelial cell, BEAS-2B." (PMID 31847356, 2019). "Importantly, our study identified seven novel methylated candidates in lung cancer, including HLTF, ID4, BNIP3, H2AFX, CACNA1G, CACNA1A and TGIF." (PMID 20849603, 2010). "In this study, we demonstrated that Id4 could interact with Slug, inhibit its binding to the E-box (sequence: CANNTG) promoter region, induce the expression of E-cad, promote the occurrence of mesenchymal-epithelial transition, and suppress lung cancer metastasis." (PMID 31847356, 2019).
colorectal cancer (10 papers, 2008 to 2023). A primary or metastatic malignant neoplasm that affects the colon or rectum. "The specific mechanism underlying the Id4-mediated regulation of proliferation, invasion, and metastasis of colorectal cancer (CRC) cells is still largely unclear." (PMID 33936204, 2021). "Up to now loss of the ID4 protein expression was observed in sporadic breast adenocarcinomas and colorectal carcinomas." (PMID 18513385, 2008). "Conversely to that observed in brain tumors, reduced Id4 expression due to promoter hypermethylation was observed in gastric and colorectal carcinomas, indicating a possible role of Id4 in tumor suppression." (PMID 21293053, 2010). "Epigenetic silencing (promoter hyper-methylation) of Id4 in cancers from different organs such as in T-/natural killer acute lymphoblastic leukemia, gastric, breast and colorectal cancers suggests its role as a putative tumor suppressor." (PMID 19500415, 2009). "Up to now, epigenetic silencing of ID4 has been demonstrated only for gastric adenocarcinoma and colorectal carcinoma cell lines." (PMID 18513385, 2008). "Epigenetic inactivation of the ID4 gene through promoter methylation has been shown for several human tumour types such as gastric carcinoma, colorectal carcinoma and acute leukaemia." (PMID 18513385, 2008). "Several studies reported a potential correlation between ID4 promoter methylation and tumour initiation/progression, e.g. in colorectal carcinoma, human leukaemia and prostate cancer." (PMID 18513385, 2008). "ID4 may inhibit colorectal cancer cell growth, epithelial–mesenchymal transition, and metastasis, thus inhibiting the PI3K/AKT pathway." (PMID 36661515, 2023).
ovarian carcinoma (10 papers, 2010 to 2022). A malignant neoplasm originating from the surface ovarian epithelium. "Incidentally, the ID4 gene is amplified in ovarian cancer; moreover, an ID4-specific tumor-penetrating nano-complex can suppress cancer growth and significantly improve the survival of tumor-bearing mice." (PMID 35740568, 2022). "In this regard, Ren and colleagues synthesized a complex delivery system containing the cyclic nonapeptide LyP-1 (CGNKRTRGC)-siRNA targeting GFP (siGFP) to evaluate the applicability of ID4 as a therapeutic target of ovarian cancer." (PMID 34575464, 2021). "In this study, we show that expression of the ID4 protein is induced in macrophages cultured with conditioned growth medium from breast and ovarian cancer cells." (PMID 32054109, 2020). "To investigate the molecular function of ID4, we first examined ID4 protein expression and cellular localisation across a panel of breast and ovarian cancer cell lines." (PMID 32527287, 2020). "Subsequently, ID4 was recognized as necessary for the proliferation and survival of ovarian cancer cells using data from Project Achilles." (PMID 33488950, 2020). "Though further studies our required to dissect the precise involvement of ID4 in the DNA damage response, these novel insights expand upon our current understanding of the mechanism by which ID4 drives malignancy in breast and ovarian cancer." (PMID 32527287, 2020). "An initial clue to the involvement of ID4 in ovarian cancer was documented through an inverse genomics study that identifies the function of a gene based on the phenotype observed upon altering the gene." (PMID 33488950, 2020). "More than a decade ago it was experimentally demonstrated in a human ovarian cancer cell line system that ID4 was a potent negative regulator of BRCA1." (PMID 27077368, 2016). "One recent study has detected ID4 as an oncogene in ovarian cancer, and demonstrated that it is a valid therapeutic target." (PMID 25642713, 2015). "This ovarian cancer study, and others, have provided some insights into the possible mechanistic roles of ID4 in cancer." (PMID 25642713, 2015). "The pan-cancer (PANCAN) normalized RNA sequencing (RNA seq; Illumina HiSeq, Illumina, Inc., San Diego, CA, USA) TCGA dataset (n = 7083) revealed decreased levels of ID 1–3 and increased levels of ID4 gene expression in ovarian cancer as compared to other cancers." (PMID 35740568, 2022). "In fact, ID4 is particularly highly upregulated in ovarian cancer." (PMID 35740568, 2022). "Furthermore, ID 1–4 genes were hypomethylated, but E2A was hypermethylated, and in ovarian cancer the expression level of ID-4 mRNA increased while that of E2A mRNA decreased." (PMID 35740568, 2022). "One of the main oncogenes in human ovarian cancer is inhibitor of DNA binding 4 (ID4)." (PMID 34575464, 2021). "Silencing of ID4 in ovarian cancer cells reduced proliferation by inducing apoptosis." (PMID 33488950, 2020). "The chromosomal region containing ID4 (6p22) is amplified in 32% of high-grade serous ovarian cancers (HG-SOC), and ID4 is over-expressed in most primary ovarian cancers and ovarian cancer cell lines, but not in normal ovaries." (PMID 32054109, 2020). "ID4 is an ovarian oncogene that is over-expressed in most primary ovarian cancers but not in normal ovary, fallopian tube and other tissues." (PMID 24676469, 2014). "Variable ID4 protein expression was observed across the ovarian cell lines, and unlike in BLBC, ID4 did not associate specifically with HGSOC, the more aggressive ovarian cancer subtype." (PMID 32527287, 2020). "ID4 is amplified in 32% of 489 HGSOC tumors and is overexpressed in ovarian cancer cell lines and tumors, but is not expressed in normal ovary and fallopian tube." (PMID 33488950, 2020). "The methylation frequencies of RASSFIA, CDH13, CACNA1A, HIN-1, DKN2B, sFRP5, ID4, and ESR were significantly higher in the clear-cell type of ovarian carcinoma than in the non-clear-cell type." (PMID 22871047, 2012).
ovarian carcinoma (continued). "Moreover, the methylation frequencies of RASSFIA, CDH13, CACNA1A, HIN-1, DKN2B, sFRP5, ID4, and ESR were significantly higher among OCCA than those in non-clear-cell types of ovarian carcinoma." (PMID 22871047, 2012).
breast tumors (8 papers, 2008 to 2022). "We observed that in ER+ breast tumors, high ID4 expression was associated with better probabilities of survival." (PMID 30139383, 2018). "Recently, Nasif and his colleague demonstrated that Id4 is significantly methylated in ER+ breast tumors." (PMID 31847356, 2019). "We show here that ID4 is silenced in breast tumors through promoter methylation and that ID4 is methylated as tumors become ER+." (PMID 30139383, 2018). "Taken together, our results show that ID4 expression differs according to the ER status, and that its expression is significantly lower in ER+ breast tumors." (PMID 30139383, 2018). "ER+ breast tumors present a significant reduction in ID4 expression as compared to ER− tumors and to normal tissue (p < 0.001)." (PMID 30139383, 2018). "Taken all together, from our in silico analyses, we can so far propose that in ER+ breast tumors, ID4 behaves as a tumor suppressor gene epigenetically regulated by DNA methylation." (PMID 30139383, 2018). "Data mining analysis revealed that ID4 expression is significantly downregulated in ER+ breast tumors as compared with ER− tumors or normal tissue." (PMID 30139383, 2018). "The comparison of ID4 expression in breast tumours versus normal breast tissues resulted in 82.6% downregulation in tumour samples by the fold change two (FC 2) approach." (PMID 18513385, 2008). "ID4 expression is significantly lower in luminal A (n = 434) and luminal B (n = 194) subtypes (both ER+) as compared with basal-like (n = 142) and normal-like breast tumors (n = 119) (both ER−) (p < 0.001)." (PMID 30139383, 2018). "Interestingly, ID4 expression is significantly higher in normal tissue with respect to breast tumors either they are ER+ or ER−." (PMID 30139383, 2018). "We hypothesize that ID4 behaves as both a tumor suppressor and an oncogene as well and that the difference in behavior varies according to the ER status of breast tumors." (PMID 30139383, 2018). "We first aimed to study the expression of ID4 across breast tumors with different ER status." (PMID 30139383, 2018). "In addition, we performed correlations of ID4 promoter methylation with ID4 mRNA and ID4 protein expression in matched samples of breast tumour and corresponding normal tissue." (PMID 18513385, 2008). "However, we and others have found the opposite role for ID4 in breast tumors." (PMID 30139383, 2018). "Furthermore, our previous observation that upregulation of TCF8 (ZEB1) occurs in metastatic and more undifferentiated breast tumours of the Vańt Veer's series suggest a potential link between E47/ID1 or ID4 and TCF8 expression in undifferentiated basal-like tumours." (PMID 23555842, 2013). "Upregulation of Id4 transcripts were also previously observed in MDCK cells overexpressing E47, although to a lower extent than Id1, supporting also the correlation between ID4 and TCF3 upregulation in basal breast tumours." (PMID 23555842, 2013). "To further examine the role of ID4 in cancer stemness, we knocked down ID4 in MDA-MB-468 breast tumor cells using SMARTpool siRNAs, and tested the expression of a panel of stemness genes including Twist1, Twist2, Snail, Slug, BMP2, IRF1, SOX4, Foxk1 and Notch3." (PMID 36291790, 2022). "Whether ID1 and ID4 play non-redundant or complementary actions on EMT and/or the basal phenotype and chemoresistance of breast tumours remains to be established in future studies." (PMID 23555842, 2013).
triple-negative breast carcinoma (8 papers, 2014 to 2024). An invasive breast carcinoma which is negative for expression of estrogen receptor (ER), progesterone receptor (PR), and human epidermal growth factor receptor 2 (HER2). "ID4 is a proto-oncogene overexpressed in the basal-like subtype of triple-negative breast cancer (TNBC), where it promotes angiogenesis, cancer stem cells, and BRACA1 misfunction." (PMID 38321003, 2024). "In this context, we analyzed the expression and role of ID4, a prognostic marker expressed by triple negative breast cancer cells that induces, upon co-culture, the M2 polarization of human PBMC monocytes." (PMID 33435455, 2021). "We recently reported that ID4 expression correlates with macrophage recruitment in triple-negative breast cancer (TNBC)." (PMID 32054109, 2020). "We performed IHC analysis of ID4 protein and macrophage marker CD68 in a triple-negative breast cancer series." (PMID 29921315, 2018).
acute lymphoblastic leukemia (7 papers, 2009 to 2023). Leukemia with an acute onset, characterized by the presence of lymphoblasts in the bone marrow and the peripheral blood. "The pan-cancer study reported mutation in SIX1, TAL1, and ID4 were present in the Wilms Tumors, T-lineage acute lymphoblastic leukemias, and B-lineage acute lymphoblastic leukemias, respectively." (PMID 31681566, 2019). "Additionally, activating translocations of ID4 have been detected in some patients and a subset of acute lymphoblastic leukemia." (PMID 20070914, 2010). "In parallel, we detected repression of pro-apoptotic mediator/tumor suppressors ID4 and ARID5B, downregulation of which correlates with enhanced acute lymphoblastic leukemia (ALL) cell proliferation." (PMID 37680627, 2023).
gastric cancer (7 papers, 2008 to 2025). A primary or metastatic malignant neoplasm involving the stomach. "Prior studies showed loss of ID4 expression in about 30% of gastric cancer as well as a means to upregulate ID4 using 5aza in gastric cell lines." (PMID 21194482, 2010). "Here, by integrating transcriptome and epigenetic multi-omics analyses of gastric tissues and mouse models, we identified that inhibitor of differentiation 4 (ID4) was downregulated in H. pylori-infected gastric tissues and associated with prognosis of gastric cancer (GC)." (PMID 41057303, 2025). "For example, lncSnhg7 promotes pancreatic cancer proliferation through ID4 by sponging miR-342-3p and promotes the proliferation of gastric cancer cells by repressing the P15 and P16 expression." (PMID 35087510, 2021). "There is evidence showing that Id4 promoter is hypermethylated in about 30% of primary gastric cancers, and Id4 expression is downregulated in most gastric cancer cell lines due to the hypermethylation in its promoter region." (PMID 33936204, 2021). "Id4 gene promoter is hypermethylated in 30% of primary gastric cancers, and Id4 expression is downregulated in most gastric cancer cell lines due to the hypermethylation of the promoter region." (PMID 33936204, 2021). "Id4 has also been found to be epigenetic silencing in many cancers such as squamous cell carcinoma, gastric cancer, and CRC, which is ascribed to the promoter hypermethylation." (PMID 33936204, 2021).